LMX1A (LIM homeobox transcription factor 1 alpha)
Diseases named in the same sentence as LMX1A in open-access papers (continued):
Sharing a sentence is not in itself a finding about the gene and the disease.
tumor (continued). "Epigenetic inactivation of LMX1A abolishes the tumor suppressor function." (PMID 32751497, 2020). "We found a statistically significant association between LMX1A methylation and tumor size (p = 0.0048) but did not observe significant associations between SOX1 or ZNF177 methylation and any of the clinicopathological parameters." (PMID 31547144, 2019). "LMX1A functions as a tumor suppressor, downregulated in GC and many other cancers." (PMID 31822638, 2019). "Recent studies have proposed LMX1A as a tumor suppressor in GC and other cancers." (PMID 31822638, 2019). "Although there was great possibility that other pathways might exist, this is the first mechanistic explanation for the tumor suppressive role of LMX1A." (PMID 31557193, 2019). "Additionally, overexpression of LMX1A partly rescued the miR‐499a‐5p‐induced tumour‐suppressive effects through elevating the NLRC5 expression." (PMID 31207033, 2019). "The evidence of LMX1A’s role as a tumor suppressor is piling up." (PMID 31557193, 2019). "In this study, we found that VAX1 and LMX1A methylation was highly associated with tumor recurrence, suggesting that methylated VAX1 and LMX1A may serve as useful biomarkers to predict BC recurrence." (PMID 22529986, 2012). "Consistently, analysis of accessible genomic fragments from scATAC-seq data revealed enrichment of LMX1A and LMX1B binding motif in tumor cells." (PMID 40128799, 2025). "Knockdown of Lmx1a and/or Lmx1b dramatically decreased Ki-67 expression in tumor cells, indicating that LMX1A and LMX1B are required for tumor cell proliferation." (PMID 40128799, 2025). "Several genes previously reported as subgroup-specific drivers or tumor lineage markers, such as PTCH1, PDE1C, and ST18 in SHH and OTX2, EOMS, and LMX1A in G3, were recovered and detected as DEGs exclusively in GNP and RL, respectively." (PMID 41029754, 2025). "Consistently, SOX2 maintains progenitor identity through regulating their expression in CP tumors and during development, whereas LMX1A and LMX1B support SOX2 functions in tumor cell proliferation." (PMID 40128799, 2025). "In agreement, knockdown of Sox2 markedly decreased LMX1A and LMX1B expression in NOTCH-driven CP tumor cells." (PMID 40128799, 2025). "In agreement, SOX2 is critical in regulating the expression of LMX1A and LMX1B in tumor cells as well as progenitors in the rhombic lip, whereas LMX1A and LMX1B mediate SOX2 functions in tumor cells." (PMID 40128799, 2025). "Together, these results indicate that LMX1A and LMX1B act downstream of SOX2 to support tumor cell proliferation, whereas NOTCH inhibition suppresses SOX2-LMX1 signaling in CP tumor cells." (PMID 40128799, 2025). "While Group 3 tumors mainly expressed photoreceptor markers, Group 4 tumor cells expressed mainly UBC markers, including EOMES, OTX2, NNAT, and LMX1A consistent with their proposed cells of origin." (PMID 39659836, 2024). "In this study, we demonstrated that promoter methylation of LMX1A was frequent in NSCLC cell lines and tumor tissues." (PMID 32751497, 2020). "Among the potential LMX1A target genes, angiopoietin-like 4 (ANGPTL4) has been reported to be an important tumor suppressor and thus was selected for further validation and research." (PMID 31557193, 2019). "At protein level, the expression of LMX1A, LMX1B, and SOX2 was markedly elevated in tumor cells." (PMID 40128799, 2025). "However, LMX1A did not function as a tumor suppressor in other types of cancer." (PMID 32751497, 2020). "However, Sox2 knockdown failed to reduce Ki-67 expression in tumor cells with virus-mediated overexpression of LMX1A or LMX1B, suggesting that LMX1 transcription factors support NOTCH-driven CP tumor cell proliferation in the absence of SOX2." (PMID 40128799, 2025).
cancer (14 papers, 2012 to 2025). A tumor composed of atypical neoplastic, often pleomorphic cells that invade other tissues. "LMX1A gene promoter hyper-methylation in human cancers could be one important cause of its downregulation." (PMID 31822638, 2019). "To further explore the potential mechanism responsible for LMX1A suppression of cancer cell invasion, we performed a NanoString gene expression analysis to investigate differentially expressed genes related to cancer progression upon LMX1A overexpression." (PMID 32751497, 2020). "In brief, promoter methylation leads to the silencing of LMX1A and contributes to cancer progression." (PMID 32751497, 2020). "In AGS cells, restoring miR-9 expression by lv-miR-9 reversed LV-LINC00682-induced LMX1A upregulation and cancer cell inhibition." (PMID 31822638, 2019). "In cancer, LMX1A has been shown to be a poor prognostic indicator in ovarian and pancreatic tumors but LMX1A was also recently shown to inhibit cell proliferation, migration, invasion, and colony formation in vitro." (PMID 26504848, 2015). "LMX1A expression was downr egulated in cancer cell lines compared to normal lung tissue." (PMID 32751497, 2020). "Recently, LMX1A has also been reported to play an important role in cancer." (PMID 32751497, 2020). "LMX1A downregulation is detected in GC and many other cancers." (PMID 31915311, 2020). "Later on, evidence for the role of LMX1A in cancers has been found." (PMID 31557193, 2019). "Lmx1a is methylation-silenced in various carcinoma and could act as a suppressor of metastasis, invasion and epithelial-mesenchymal transition in cancer cells." (PMID 27081082, 2016). "Here, we assessed whether LMX1A inhibited cancer invasion through EMT using qRT-PCR in H23 cells." (PMID 32751497, 2020). "We thought that LMX1A increased the level of ANGPTL4, thus depress the expression of C-myc and reduce the cell proliferation of cancer cell." (PMID 31557193, 2019).
neurological disorders (2 papers, 2020 to 2022). "Lmx1a and Lmx1b have been closely associated with neurological disorders, and it is important to know their exact role in maintaining vmDA neurons." (PMID 35269474, 2022). "LMX1A codes for a growth factor that is involved in development of brainstem and cerebellum structures and has been linked to psychiatric and neurological disorders, including SCZ and PD43." (PMID 32782260, 2020).
LMX1A also shares sentences with these, for which no sentence is quoted: gastric tumor (2 papers); ovarian tumor (2); adenocarcinoma (1); benign ovarian tumors (1); breast carcinoma (1); Cardiovascular Disease (1); dementia (1); diffuse type adenocarcinoma (1); endolymphatic hydrops (1); Hearing impairment (1); hepatocellular carcinoma (1); Hydrocephalus (1); Hyperglycemia (1); Insulin resistance (1); Lesch-Nyhan disease (1); lung adenocarcinoma (1); lung squamous cell carcinoma (1); malignant mesothelioma (1); meningioma (1); metastatic tumor (1); Moebius syndrome (1); neuroblastoma (1); otosclerosis (1); Parkinsonism (1); prostate carcinoma (1); rectal adenocarcinoma (1); Stickler syndrome type 1 (1); Stroke (1); T-cell acute lymphoblastic leukemia (1); Tinnitus (1).
A further 3 diseases each share a sentence with LMX1A in 1 paper.